SHLD3 (shieldin complex subunit 3)
Description:
Component of the shieldin complex, which plays an important role in repair of DNA double-stranded breaks (DSBs). During G1 and S phase of the cell cycle, the complex functions downstream of TP53BP1 to promote non-homologous end joining (NHEJ) and suppress DNA end resection. Mediates various NHEJ-dependent processes including immunoglobulin class-switch recombination, and fusion of unprotected telomeres.
Synonyms: FLJ26957; RINN1; AC008560.1; CTC-534A2.2
Tractability: Small molecule: a structure with a bound ligand is known.
Gene: Protein-coding gene on chromosome 5 (65,624,765 to 65,630,928, forward strand). Ensembl gene ENSG00000253251.
Subcellular location: Chromosome
Subcellular location (Human Protein Atlas): Nucleoli; Nucleoplasm
Gene Ontology:
Molecular function: protein binding
Biological process: negative regulation of double-strand break repair via homologous recombination; positive regulation of double-strand break repair via nonhomologous end joining; positive regulation of isotype switching; somatic diversification of immunoglobulins involved in immune response; telomere maintenance in response to DNA damage; regulation of double-strand break repair via homologous recombination
Cellular component: chromosome; site of double-strand break; chromatin
Genetic constraint (gnomAD): Loss-of-function variants: 15 observed, 22.66 expected, observed/expected ratio (o/e) 0.66, 90% interval 0.44 to 1.02. The upper end of that interval is the gene's LOEUF score, 1.02, which puts it in group 4 of 6, group 1 being the genes least tolerant of losing a copy. Missense variants: 273 observed, 299.44 expected, observed/expected ratio (o/e) 0.91, 90% interval 0.82 to 1.01. Synonymous variants: 103 observed, 102.85 expected, observed/expected ratio (o/e) 1, 90% interval 0.85 to 1.18.
Homologues: Orthologues: macaque SHLD3 (96% identical), pig SHLD3 (86% identical), rat Shld3 (76% identical), mouse Shld3 (74% identical), tropical clawed frog SHLD3 (40% identical), zebrafish zgc:101664 (28% identical).
Diseases named in the same sentence as SHLD3 in open-access papers:
SHLD3 is named in the same sentence as 4 diseases in open-access papers, as found by Europe PMC text mining. Sharing a sentence is not in itself a finding about the gene and the disease. The quoted sentences say what the papers report.
B cell lymphoma (1 paper, 2024). "For this, we introduced TwinStrep-tagged Shld1 and Shld3 transgenes into Shld1−/− and Shld3−/− CH12-F3 mouse B cell lymphoma cell lines, respectively, and validated functional complementation at the level of rescued IgM-to-IgA class switching in stimulated cell cultures." (PMID 39227718, 2024).
cancer (1 paper, 2024). A tumor composed of atypical neoplastic, often pleomorphic cells that invade other tissues. "Recent studies have shown that, in human cancer cells, the tetrameric Shieldin complex (comprising REV7, SHLD1, SHLD2, and SHLD3) facilitates non-homologous end-joining (NHEJ) while blocking homologous recombination (HR)." (PMID 39630591, 2024).
tumor (1 paper, 2024). "The genes Herc6, Kat7, Mef2c, Rbm15, and Shld3 were found to be upregulated in both the right and left tumors of the treated groups, suggesting a coordinated response in tumor inhibition." (PMID 39339213, 2024).
SHLD3 also shares sentences with these, for which no sentence is quoted: mammary tumor (1 paper).